RNU6-548P (RNA, U6 small nuclear 548, pseudogene)
Gene: Small nuclear RNA gene on chromosome 2 (64,994,746 to 64,994,860, forward strand). Ensembl gene ENSG00000252892.
Homologues: Orthologues: chimpanzee U6 (100% identical), macaque U6 (93% identical). Paralogues in human: RNU6-16P (80% identical), RNU6-1005P (79% identical), RNU6-73P (79% identical), RNU6-12P (78% identical), RNU6-13P (78% identical), RNU6-32P (78% identical), RNU6-480P (78% identical), RNU6-1 (77% identical), RNU6-1029P (77% identical), RNU6-1181P (77% identical), RNU6-17P (77% identical), RNU6-18P (77% identical), and 1285 more.